NCOR1 (nuclear receptor corepressor 1)
Diseases named in the same sentence as NCOR1 in open-access papers (continued):
Sharing a sentence is not in itself a finding about the gene and the disease.
atherosclerosis (continued). "Since NCOR1 transrepresses the function of several nuclear receptors involved in hepatic lipid transport and synthesis, we hypothesized that genetic NCOR1 deletion in the liver alters lipid metabolism and atherosclerosis development." (PMID 37349757, 2023). "Further studies are needed to elucidate if and how GADD45A, NCOR1 and PON2 are involved in the development of accelerated atherosclerosis in RA." (PMID 30138371, 2018). "In contrast, the atherosclerosis plaques of MHD3KO mice displayed an enhanced collagen distribution and expanded protective fibrous caps, whereas the atherosclerotic plaques of myeloid cell-specific NCoR1 knockout animals exhibited increased necrotic cores." (PMID 37674539, 2023).
bladder cancer (10 papers, 2013 to 2025). "Mutations in NCOR1 have been also described in other solid tumors, like colorectal cancer or bladder cancer." (PMID 30485330, 2018). "The involvement of NCOR1 in other human cancers such as breast and bladder cancers was demonstrated by a close association of NCOR1 abnormal expression with cancer development." (PMID 23840792, 2013). "Mutations or deletions of NCOR1 have been described in bladder cancer." (PMID 33763074, 2021). "NCOR1 mutations may be a potential biomarker for predicting the prognosis of bladder cancer patients undergoing ICI treatment." (PMID 33763074, 2021). "The results indicated that NCOR1 mutations may be a potential biomarker for bladder cancer patients receiving ICIs." (PMID 33763074, 2021). "In bladder cancer, NCOR1 alterations correlate with the efficacy of immune-checkpoint blockade therapy, indicating its potential as an immunotherapy biomarker." (PMID 39948683, 2025). "In bladder cancer cells, elevated Nuclear Receptor Co-repressor 1 (NCOR1) expression generates an epigenetic lesion that is associated with increased cellular invasiveness and attenuated anti-proliferative receptor responses." (PMID 30875794, 2019). "NCOR1-MT tumors were related to longer OS in bladder cancer patients after ICI treatment." (PMID 33763074, 2021). "Therefore, we explored various mechanisms of the response to ICIs based on NCOR1 status in bladder cancer, which may serve as a future potential biomarker." (PMID 33763074, 2021). "Increased NCOR1 and NCOR2/SMRT expression occurs also in breast and bladder cancer and suppressed the responsiveness of nuclear receptors that exert mitotic restraint, such as VDR and PPARα,γ." (PMID 23098689, 2013). "Third, there is currently no direct evidence of NCOR1 transcriptomics, CNV and protein levels and other data related to the prognosis of ICI treatment of bladder cancer patients." (PMID 33763074, 2021).
colorectal cancer (9 papers, 2015 to 2025). A primary or metastatic malignant neoplasm that affects the colon or rectum. "NCOR1 point mutations have also been detected in two colorectal cancer cell lines." (PMID 34503224, 2021). "Functional analysis demonstrated that NCOR1 is required for colorectal cancer cell growth and protects against cellular senescence, while loss of NCOR1 reduced tumorigenic growth in vivo." (PMID 34680332, 2021). "This study demonstrated that NCOR1 is required for colorectal cancer cell growth." (PMID 34503224, 2021). "We hypothesized that NCOR1 could control colorectal cancer cell proliferation and tumorigenicity." (PMID 34503224, 2021). "Protein factors that could regulate transcription of SMAD4-213 via AnnoLnc2 predicted binding sites upstream of/overlapping TSS that are expressed in colorectal cancer are CDX2, CEBPB, ELF1, NCOA1, NCOR1, NCOR2 and TFAP4." (PMID 39132157, 2024). "We found that NCOR1, NONO, and PPP1CC were more highly expressed in right-sided colorectal cancer, while CLDN4, EGR1, and ID2 were more highly expressed in left-sided colorectal cancer." (PMID 41174721, 2025).
glioma (9 papers, 2015 to 2025). A benign or malignant brain and spinal cord tumor that arises from glial cells (astrocytes, oligodendrocytes, ependymal cells). "EV-miR-1587 from glioma-associated MSCs promotes the proliferation and clonogenicity of glioma stem-like cells by targeting NCOR1." (PMID 32503543, 2020). "Glioma-associated mesenchymal stem cells secreted miR-1587 via exosomes, targeting, and reducing the expression of NCOR1 to promote proliferation and colony formation and increase cells tumorigenicity of glioma stem cells." (PMID 31652445, 2019). "In glioma stem cells (GSCs), miR-1587 and miR-3620-5p increase the proliferation and miR-1587 inhibits the hormone receptor co-repressor-1 (NCOR1) after EVs transfers." (PMID 32178454, 2020). "Additionally, the strong nuclear expression of HDAC1, HDAC2, and NCOR2 in glioma cells, along with weak expression of NCOR1 and HDAC3, suggests a potential role for these proteins in tumor progression and as markers for patient prognosis." (PMID 40940748, 2025). "Hsa-miR-1587 could be secreted through exosomes released by glioma-associated mesenchymal stem cells, and the downstream molecule NCOR1 was suppressed in glioma stem cells, leading to the enhancing proliferation, colony formation, and promoting tumor progression." (PMID 34639058, 2021). "In glioma cells, strong nuclear expression of HDAC1, HDAC2, and NCOR2 has been observed, while NCOR1 and HDAC3 show weaker expression." (PMID 40940748, 2025).
Hepatic steatosis (9 papers, 2019 to 2024). Steatosis is a term used to denote lipid accumulation within hepatocytes. "Our data suggest that selective degradation of NCoR1 by CMA is decreased in the liver during aging, which is linked to decreased fatty acid oxidation and development of aging-related fatty liver." (PMID 37524243, 2023). "In conclusion, we determined CMA activity in the aged liver and discovered that CMA inhibition and NCoR1-mediated PPARα inactivation are responsible for aging-related fatty liver." (PMID 37524243, 2023). "Taken together, HDAC3 and NCoR1 KO in the liver contributes to metabolic imbalances, resulting in hepatic steatosis, insulin resistance, altered glucose and lipid metabolism." (PMID 37674539, 2023). "LAMP2A knockdown in the mouse liver resulted in hepatic steatosis, demonstrating that the NCoR1/PPARα pathway inhibited fatty acid oxidation." (PMID 37524243, 2023). "While previous studies have focused on the role of NCoR1 in tumor development, we demonstrated that NCoR1 may also play a role in aging-related fatty liver disease." (PMID 37524243, 2023). "Increased JNK activation with the progression of hepatic steatosis reduces peroxisome β-oxidation by suppressing peroxisome proliferator-activated receptor α (PPARα) activity, in part through the upregulation of nuclear receptor corepressor 1 (NCoR1)." (PMID 36009582, 2022). "Interestingly, global SMRT deletion causes hepatic steatosis via the activation of the obesity seen rather than through the de novo activation of lipogenic gene transcription as is seen in the hepatic specific deletion of NCoR1." (PMID 31404087, 2019). "However, NCoR1 IKO mice still exhibited improvements in the circulating TG and cholesterol levels and hepatic steatosis." (PMID 39807334, 2024). "Importantly, hepatic deletion of both NCoR1 function and SMRT leads to substantial hepatic steatosis demonstrating that both CoRs cooperatively act to suppress hepatic lipid synthesis." (PMID 31404087, 2019). "This is unlike NCoR1 deletion, which results in hepatic steatosis due to the upregulation of lipogenic gene expression." (PMID 31404087, 2019).
leukemia (9 papers, 2011 to 2024). A malignant (clonal) hematologic disorder, involving hematopoietic stem cells and characterized by the presence of primitive or atypical myeloid or lymphoid cells in the bone marrow and the blood. "Importantly, flawed NCoR1/2 activity has been linked to various diseases, including several types of leukaemia and other cancers." (PMID 37137875, 2023). "The TNF-alpha, SIN3 and NCOR1 related complex were reported to have close relationship with leukemia." (PMID 26822725, 2016).
breast tumors (8 papers, 2011 to 2023). "We identified that NCOR1 is mutated in more than 3% of breast tumors and lung adenocarcinomas and linked with detrimental outcome in some subtypes." (PMID 30485330, 2018). "As shown, NCOR1 was mutated in 3.76% of all breast tumors, and in 3.65% of basal-like, 2% of Luminal A, 2.45% of Luminal B, and 3.33% of HER2 positive." (PMID 30485330, 2018). "NCOR1 has been deeply studied in estrogen receptor positive breast tumors." (PMID 30485330, 2018). "Moreover, VDR expression were remarkably lower in ER- than in ER+ breast tumors, and the elevation of VDR nuclear corepressor NCoR1 level was particularly associated with ER negativity." (PMID 21386992, 2011).
Obesity (8 papers, 2016 to 2024). Accumulation of substantial excess body fat. "Together, these results showed that NCoR1 deficiency in IECs markedly attenuated obesity and metabolic syndrome in mice with diet-induced obesity." (PMID 39807334, 2024). "Here, we demonstrated that the deletion of NCoR1 in intestinal epithelial cells (IECs) prevented mice from developing diet-induced metabolic syndrome and obesity." (PMID 39807334, 2024). "To assess the therapeutic effect of NCoR1 deletion in IECs on obesity and metabolic syndrome after disease onset, we generated inducible NCoR1-knockout mice (NCoR1ΔIECi mice) utilizing vil-Cre-ERT2 mice." (PMID 39807334, 2024). "Our study revealed that intestinal-specific deletion of the corepressor NCoR1 induced robust improvements in obesity and metabolic syndrome by simultaneously decreasing the energy/lipid intake and enhancing the energy expenditure." (PMID 39807334, 2024). "NCoR1-DADm mice, when fed with high-fat diet, were resistant to obesity and developed insulin resistance while having decreased hepatic glucose production." (PMID 37674539, 2023). "Any deficiencies or dysregulations of NCoR1, NCoR2, and HDAC3 have been associated with metabolic diseases such as obesity, type 2 diabetes, and NAFLD." (PMID 37674539, 2023). "Second, the use of the experimental diets: High-fat diet to study the impact of NCOR1 on diet-induced obesity versus high-cholesterol diet to assess atherogenesis." (PMID 33117357, 2020). "Paradoxically, the in vivo myeloid cell-specific deletion of Ncor1 repressed inflammatory gene expression and improved insulin sensitivity in a diet-induced obesity mouse model." (PMID 33117357, 2020). "Dysregulation of this HDAC3 and NCoR1/2 complex can contribute to the development of metabolic syndrome, a cluster of interconnected metabolic abnormalities, including insulin resistance, dyslipidemia, and obesity." (PMID 37674539, 2023). "Therefore, intestinal NCoR1 may serve as a potential new drug target for treating obesity and metabolic syndrome." (PMID 39807334, 2024). "The deletion of NCoR1 in IECs activated PPARα and LXR, and together, these two signaling pathways changed the energy balance to reduce anabolism and increase catabolism, thereby alleviating obesity and metabolic syndrome." (PMID 39807334, 2024). "Together, these data demonstrated that the effects of NCoR1 on obesity and metabolic syndrome did not rely on gut microbiota activity." (PMID 39807334, 2024).
melanoma (7 papers, 2015 to 2025). A malignant, usually aggressive tumor composed of atypical, neoplastic melanocytes. "NCOR1 was also found mutated, lost, or with aberrant localization in several human cancers such as bladder, breast, prostate, retinoblastoma, and malignant melanoma." (PMID 34680332, 2021). "In addition to mutations, aberrant cytoplasmic localization in NCOR1 has been described in CRC, retinoblastoma, and malignant melanoma." (PMID 34503224, 2021). "In melanoma, TBX2 binding with the PRC1.1 complex and nuclear receptor corepressor 1/2 (NCOR1/2) exerts anti-senescence and proliferation-promoting effects on tumor cells." (PMID 38965548, 2024).
anaemia (6 papers, 2012 to 2023). "The KH patient with an NCOR1 mutation had iron deficiency anemia as additional feature, likely due to hepcidin overexpression." (PMID 35422763, 2022). "The KH patient with an NCOR1 mutation had loose stools and iron deficiency anemia as additional features, the latter possibly caused by hepcidin overexpression." (PMID 33849624, 2021). "In accordance with our hypothesis, NCOR1-deficient mice showed abnormal FL erythropoiesis and developed severe anaemia during mid-gestation." (PMID 26593974, 2015). "Ncor1−/− mice exhibit anemia at E13.5, and the severity of the anemia increases with age, resulting in eventual death." (PMID 29273766, 2017). "Observations that ablation of Ncor1 or Erf in the embryo proper resulted in a shared phenotype involving impaired haematopoiesis, severe anaemia and lethality around E14.559,71, indicate that the Erf/NCoR1/2 axis may play a more general role." (PMID 37137875, 2023).
cardiac hypertrophy (6 papers, 2019 to 2023). "The Class I HDAC3 enzyme participates in the repressive activities of NCOR1, and its deficiency in cardiomyocytes causes severe cardiac hypertrophy at an early stage." (PMID 33117357, 2020). "Next, we subjected 8‐ to 12‐week‐old LC and CMNKO mice to AAC and investigated the impacts of NCoR1 deficiency on pathological cardiac hypertrophy." (PMID 31532577, 2019). "To apply our findings to the prospect of gene therapy, we tried to transfer NCoR1 into myocardium by adeno‐associated virus serotype 9 (AAV9) to examine its inhibitory effects on cardiac hypertrophy." (PMID 31532577, 2019). "Through this study, we showed that cardiomyocyte NCoR1 deficiency led to cardiac hypertrophy under physiological condition and aggravated cardiac hypertrophy under POL." (PMID 31532577, 2019). "described, NCOR1 may be considered as a stress-responsive and cardioprotective regulator during cardiac hypertrophy, showing that its deficiency led to cardiac hypertrophy under physiological condition and aggravated hypertrophy induced by pressure overload." (PMID 33117357, 2020). "Subsequently, we explored the underlying mechanisms how NCoR1 interacted with MEF2 and HDAC to regulate cardiac hypertrophy." (PMID 31532577, 2019). "Delivering RIDs of NCoR1 into myocardium is a promising therapeutic strategy to treat cardiac hypertrophy and heart failure." (PMID 31532577, 2019). "The findings support strategies targeting the NCoR1/MEF2a/HDACs complex in cardiomyocytes as potential novel approaches for the intervention of cardiac hypertrophy." (PMID 31532577, 2019). "To explore the function of NCoR1 in cardiac hypertrophy, we first detected the expression of NCoR1 in hypertrophied hearts or cardiomyocytes." (PMID 31532577, 2019). "Mechanistically, NCoR1 interacted with MEF2a and cooperated with class IIa HDACs to control cardiac hypertrophy." (PMID 31532577, 2019). "In this study, we found that cardiomyocyte‐specific NCoR1 knockout (CMNKO) mice exhibited spontaneous cardiac hypertrophy." (PMID 31532577, 2019). "Our results showed that the protein expression of NCoR1 was upregulated after hypertrophic stimulation, which we believed to be part of the adaptation during cardiac hypertrophy." (PMID 31532577, 2019). "NCoR1 deficiency led to cardiac hypertrophy under physiological conditions and worsened hypertrophy induced by pressure overload, suggesting NCoR1 may be considered as a stress-responsive and cardioprotective regulator during cardiac hypertrophy." (PMID 37674539, 2023). "In this study, the upregulation of nuclear receptor corepressor 1 (NCOR1), a transcription regulator known to recruit histone deacetylases and established repressor of cardiac hypertrophy, was proposed to account for the diminution of MEF2c in decompensated RV." (PMID 34208388, 2021). "The authors generated mutant mice with a cardiomyocyte‐specific knock‐out of NCoR1, which develop myocardial hypertrophy and impaired cardiac function at the age of 10 months, as well as in pathological cardiac overload due to abdominal aortic constriction (ACC)." (PMID 31622030, 2019). "Therefore, NCoR1 works more likely through class IIa HDACs instead of HDAC3 to affect cardiac hypertrophy." (PMID 31532577, 2019). "Finally, overexpression of RIDs of NCoR1 in the heart attenuated cardiac hypertrophy and dysfunction induced by pressure overload." (PMID 31532577, 2019). "Our study identified NCoR1/MEF2/HDACs complex as a novel target in cardiac hypertrophy." (PMID 31532577, 2019). "In our study, NCoR1 deficiency in cardiomyocytes only led to mild cardiac hypertrophy phenotype under physiological condition and did not affect triglyceride accumulation in the heart." (PMID 31532577, 2019). "It is unclear whether NCoR1 plays a role in cardiomyocytes and during cardiac hypertrophy under physiological and pathological conditions." (PMID 31532577, 2019).
cardiac hypertrophy (continued). "NCoR1 may be considered as a stress‐responsive and cardioprotective regulator during cardiac hypertrophy." (PMID 31532577, 2019). "Importantly, overexpression of RIDs of NCoR1 in myocardium inhibited POL‐induced cardiac hypertrophy and dysfunction." (PMID 31532577, 2019). "Finally, we explored the possibility of gene therapy using NCoR1 for pathological cardiac hypertrophy." (PMID 31532577, 2019). "Indeed, NCoR1 in turn served as a suppressor of cardiac hypertrophy." (PMID 31532577, 2019). "HDAC3 enzyme is involved in the repressive activities of NCoR1, and depletion of HDAC3 in cardiomyocytes results in severe cardiac hypertrophy at an early stage." (PMID 37674539, 2023). "Here, we found that cardiomyocyte‐specific NCoR1 knockout (CMNKO) mice manifested cardiac hypertrophy at baseline and had more severe cardiac hypertrophy and dysfunction after pressure overload." (PMID 31532577, 2019). "In mouse model of cardiac hypertrophy induced by angiotensin II or abdominal aortic constriction (AAC), the protein level of NCoR1 was also upregulated in hypertrophied hearts (Fig EV1D–I)." (PMID 31532577, 2019). "In conclusion, NCoR1 cooperates with MEF2 and HDACs to repress cardiac hypertrophy." (PMID 31532577, 2019). "Targeting NCoR1 and the MEF2/HDACs complex may be an attractive therapeutic strategy to tackle pathological cardiac hypertrophy." (PMID 31532577, 2019). "Although NCoR1 has been demonstrated to be an important player in transcriptional regulation in several other cell types, its function in cardiomyocytes and cardiac hypertrophy have not been elucidated." (PMID 31532577, 2019).
Rett syndrome (6 papers, 2018 to 2021). A severe neurodevelopmental disorder affecting the central nervous system. "NCOR1 is a nuclear receptor corepressor which was previously associated with Rett Syndrome and Endometrial Hyperplasia." (PMID 31849593, 2019). "Indeed, a recent crystal structure of the NID bound to the TBL1XR1 subunit, which is shared by NCoR1/2 complexes, showed that four adjacent amino acids that are individually mutated in Rett syndrome (one of which is R306) all make intimate molecular contacts with the WD40 domain of TBL1XR1." (PMID 30463906, 2018).
acute promyelocytic leukemia (5 papers, 2011 to 2025). An aggressive form of acute myeloid leukemia (AML), characterized by arrest of leukocyte differentiation at the promyelocyte stage, due to a specific chromosomal translocation t(15;17) in myeloid cells. "Such oncogenic roles of NCOR1 have been demonstrated in acute promyelocyte leukemia." (PMID 23840792, 2013).